LINC01918 (long independently transcribed non-coding RNA 1918)
Synonyms: ROSALIND
Gene: Long non-coding RNA gene on chromosome 2 (105,143,591 to 105,145,465, forward strand). Ensembl gene ENSG00000226508.
Diseases named in the same sentence as LINC01918 in open-access papers:
LINC01918 is named in the same sentence as 1 disease in open-access papers, as found by Europe PMC text mining. Sharing a sentence is not in itself a finding about the gene and the disease. The quoted sentences say what the papers report.
thyroid (1 paper, 2021). "Captured downregulated lncNRAs also included annotated transcripts not yet associated with neurodevelopment, such as LINC01918 and AL139393.2, implicated in thyroid and medulloblastoma carcinoma, respectively, as well as SMCR2, also known as lncSREBF1, which plays a role in lipid metabolism." (PMID 33445654, 2021).